INS (insulin)
Diseases named in the same sentence as INS in open-access papers (continued):
Sharing a sentence is not in itself a finding about the gene and the disease.
diabetes (continued). "The reason for poor glycaemic control in patients with a longer duration of diabetes is attributed to a decline in pancreatic function over time, leading to lower levels of insulin secretion and increased insulin resistance." (PMID 39213431, 2024). "Approximating the human glucose-insulin system is considered the hardest part of creating a diabetes simulator." (PMID 38493243, 2024). "The evolution of insulin – from animal to human forms and present-day insulin analogues – has led to increased prices, making it difficult for many people with diabetes even in high-income countries to afford the medication." (PMID 39464844, 2024). "The mean values of Glycemic Impairment (GI) metrics (FBG, insulin, and HbA1c) were lower than clinical cutoffs for diabetes mellitus, although the mean FBG of 104.79 mg." (PMID 38753844, 2024). "In most countries in Africa, point-of-care testing devices, access to insulin (and its storage) and more basic diabetes technology such as a finger stick glucometer and testing strips, are the more pressing challenges." (PMID 39703363, 2024). "Insulin pumps undergo evaluation based on many essential factors that are vital for efficient diabetes treatment." (PMID 39065641, 2024). "Inflammation targeting the endocrine islets of the pancreas results in type 1 diabetes mellitus, which can be managed through the use of exogenous insulin to replace insulin production lost following beta cell destruction." (PMID 38585277, 2024). "The scatterplot shows that patients with insulin-controlled diabetes clustered tightly, whereas those with DKA exhibited a more heterogeneous distribution, distinctly separated from the control group." (PMID 39707182, 2024). "The method for its computation was developed using the outcomes of a principal component analysis conducted on 2-week CGM profiles from 225 adults with diabetes who were on insulin therapy." (PMID 39201842, 2024). "Rapid-acting insulin analogs (RAIAs) and long-acting insulin analogs are prescribed for the effective management of diabetes." (PMID 39457586, 2024). "The brain is a primary organ that targets insulin, and disrupting insulin metabolism compromises the function of neurons and glial cells during diabetes mellitus (DM)." (PMID 39328423, 2024). "In males, [Ca2+]i dynamics progressively declined subsequent to glucose stimulation while insulin secretion continue to increase, suggesting uncoordinated beta cell function as an early sign of diabetes." (PMID 38814444, 2024). "Acute or chronic Cd exposure has been found to initiate multi-system injuries such as insulin-producing β-cell damage, immune disorder, diabetes, and diabetic retinopathy." (PMID 38903987, 2024). "Diabetes mellitus is the dysregulation of blood glucose levels due to insufficient insulin secretion by pancreatic beta cells, insensitivity of peripheral tissues to insulin, or a combination of both." (PMID 39635529, 2024). "It has been suggested that this form of diabetes is attributed to the overall impairment of pancreatic islet development and function, including a reduction in insulin (INS) production by beta cells." (PMID 39080045, 2024). "Once diagnosed with diabetes, patients need to take oral hypoglycemic drugs or use insulin to control blood sugar and slow down the progression of the disease." (PMID 38167106, 2024). "In general, diabetes is more prevalent in male than female patients, due in part to the protective role of estrogen on energy expenditure, insulin sensitivity, and adipose tissue distribution." (PMID 38313160, 2024). "Insufficient insulin secretion would result in type 1 diabetes, later-stage type 2 diabetes, and some other specific types of diabetes, where exogenous insulin supplementation is usually required for treatment." (PMID 38966749, 2024). "Diabetes mellitus is a group of metabolic disorders characterized by chronic hyper-glycemia resulting from defects in insulin secretion, insulin action, or both." (PMID 39685809, 2024).
diabetes (continued). "How does home insulin pump use managed by patients and caregivers compare with hospital-managed insulin pumps or insulin injections in hospitalized children with diabetes?" (PMID 38324312, 2024). "Bulgarian traditional medicine recommends tens of herbs to assist diabetes management; their effects are most often related to a reduction in blood glucose or stimulation of insulin secretion." (PMID 38794476, 2024). "The insulin dose to stabilize a patient with diabetes is assumed as the difference between the patient’s needs and the patient’s insulin production." (PMID 38539988, 2024). "Insulin is often considered a final option in managing type 2 diabetes mellitus (T2DM), where it enhances glucose regulation and diminishes the risks of diabetes-associated complications and death." (PMID 39272654, 2024). "Dietary fiber has been reported to significantly lower blood sugar levels and increase insulin in people with diabetes." (PMID 38844885, 2024). "Sweroside can the regulation of phosphoenolpyruvate carboxykinase gene expression and then mimic insulin to resist diabetes." (PMID 39040674, 2024). "Insulin is considered the gold standard treatment option for women with diabetes in pregnancy despite being labour intensive for women in administration and the inherent risk of hypoglycaemia." (PMID 38933924, 2024). "Data from three São Paulo outpatient centers yielded demographic and medical information from electronic records, including nationality, age, sex, clinical history, insulin use, and duration of diabetes diagnosis." (PMID 38991014, 2024). "Sulfonylurea (SU) is used to improve insulin secretion in diabetes, but it suffers from secondary failure." (PMID 38335173, 2024). "We found Autistic individuals reported autism to influence various aspects of diabetes self-management including daily tasks like taking insulin and engaging with diabetes healthcare professionals." (PMID 37480434, 2024). "HDAC6 KO mice have improved insulin signaling and glucose intolerance in dexamethasone-induced diabetes and insulin-induced models." (PMID 38534427, 2024). "Diabetes mellitus (DM) is characterized by elevated blood sugar levels, peripheral tissue resistance to insulin, and impaired functioning of pancreatic β-cells." (PMID 38715962, 2024). "We have collected cerebrovascular risk factors including BMI, fasting glucose, insulin, HOMA‐IR, C‐peptide, hypertension, diabetes, hypercholesterolemia, and smoking that linked with vascular diseases." (PMID 39258805, 2024). "Beta blockers in patients with diabetes mellitus can potentially impair insulin release or mask the catecholamine-mediated symptoms of hypoglycemia, but studies have shown use of carvedilol and bisoprolol in this population." (PMID 39093374, 2024). "Conventional therapies for both types of diabetes typically consist of frequent glucose monitoring and insulin administration (e.g., through subcutaneous injections or insulin pumps) throughout the day." (PMID 39000136, 2024). "Patients with diabetes mellitus were closely monitored, and their insulin doses were increased to correct glycemic values." (PMID 38399417, 2024). "It is known that reduced insulin secretion occurs not only in type 1 diabetes mellitus (T1DM) but also in maturity-onset diabetes of the young (MODY), which is molecularly linked to mutations in the SUR1/KIR.2.6 channel genes." (PMID 39767735, 2024). "Participants with diabetes had greater odds of hospitalization if they had heart failure, falls, amputation, and insulin treatment." (PMID 39058533, 2024). "Despite her father being normoglycemic, her mother, her maternal grandmother, and three of her maternal uncles all developed diabetes before the age of 18 and required insulin treatment." (PMID 39191897, 2024).
diabetes (continued). "In the context of monitoring insulin resistance and sensitivity, the measurement of C-peptide levels in the blood also serves as a significant biomarker of diabetes since it is secreted in equimolar amounts with insulin." (PMID 39822775, 2024). "Diabetes mellitus is a metabolic disorder characterized by elevated blood glucose levels or hyperglycemia due to abnormalities in either insulin secretion or insulin action or both." (PMID 38611884, 2024). "Two studies examined school-based diabetes medical care, one of which examined use of advanced diabetes technologies (i.e., insulin pumps, continuous glucose monitors, hybrid-closed loop insulin infusion systems) in schools." (PMID 39470899, 2024). "Type 1 diabetes mellitus (T1D) is an incurable autoimmune disease characterized by the destruction of pancreatic islet cells, resulting in lifelong dependency on insulin treatment." (PMID 39202069, 2024). "Type II diabetes mellitus prevalence, diabetes medication usage, and insulin usage by fiscal year, sex, and age group." (PMID 39356700, 2024). "It has shown efficacy in glucose control for diabetes mellitus type 2 patients by increasing insulin secretion, lowering glucagon release, and slowing gastric emptying." (PMID 38975533, 2024). "The use of diabetes medications also varied among the study population: 20% were taking insulin, 20% were taking different oral solutions, 20% were taking both oral and insulin, and 17% were managing their diabetes only through diet." (PMID 38418620, 2024). "One interesting aspect related to glucagon's role in enhancing insulin action is the development of the bionic pancreas, which combines glucagon and insulin to prevent hypoglycaemic episodes in people with diabetes." (PMID 38579770, 2024). "A group of metabolites was 10-20-fold more abundant in WLD than in WHR (p < 0.001), which potentially regulates glucose metabolism, insulin, vascular tone, or inflammation or has known therapeutic effects for diabetes or its complications." (PMID 39275152, 2024). "HbA1c, frequency of glucose monitoring, severe hypoglycemia episodes, DKA episodes, communication with a healthcare provider, prior visits with healthcare provider, and access to insulin and diabetes supplies." (PMID 39867016, 2024). "In the case of obesity, which often coexists with metabolic syndrome and diabetes, lycopene has shown potential to reduce inflammation, improve insulin sensitivity, and reduce fatty liver disease in animal studies." (PMID 39519540, 2024). "Type 2 diabetes mellitus is characterized by insulin resistance, decreased insulin secretion, and elevated hepatic glucose synthesis at varying levels." (PMID 39057600, 2024). "One-fifth of patients were treated for diabetes mellitus, chiefly with insulin, DPP-4 inhibitors, metformin, and glinides." (PMID 38999282, 2024). "With the ongoing increase in diabetes prevalence in India, there is a growing demand for cost-effective biosimilar insulin options." (PMID 38910730, 2024). "Acute kidney injury was more prevalent among those who had transfusion reactions (14.7%) than among those who did not (7.8%), p = < 0.01; those with AKI had a higher frequency of diabetes, vasopressors, and insulin use." (PMID 38285316, 2024). "In fact, a dysfunction in insulin signaling, such as in conditions of insulin resistance or diabetes, results in the accumulation of βA plaques and tau protein tangles, which are characteristic of AD." (PMID 39273520, 2024). "In terms of glycemic and insulinemic balance, women are more insulin-sensitive than men, but this metabolic benefit gradually diminishes after menopause or when insulin resistance develops into hyperglycemia and diabetes." (PMID 38794646, 2024). "In the case of insulin, in particular, oral administration is considered the most advantageous in treating diabetes because it closely mimics endogenous insulin secretion." (PMID 39000136, 2024).
diabetes (continued). "Deterioration of β-cell insulin secretion has been shown to precede the progression from pre-diabetes to type 2 diabetes." (PMID 39280605, 2024). "Future demand for economical insulin is predicted to significantly grow because of the rising prevalence of diabetes and the development of alternative delivery systems that need greater dosages." (PMID 39309966, 2024). "Another advancement is the development of smart insulin pens, which track insulin doses and provide reminders to patients, helping them manage their diabetes more effectively." (PMID 39246894, 2024). "The increased prevalence of diabetes with age in pwCF suggests a gradual decline in insulin production and/or reduced insulin sensitivity, which is preceded by impaired glucose tolerance for years." (PMID 39620135, 2024). "Ten of the T2D patients had previously been diagnosed with diabetes and were using statins or sulfonylureas or a combination of drugs (statins, sulfonylureas, insulin and/or hypertensive drugs)." (PMID 39649174, 2024). "Knockdown Hsp90ab1 in the mouse model of diabetes demonstrated the key role of this gene in controlling diabetes-mediated signaling pathways such as glucose metabolism and insulin signaling." (PMID 38931172, 2024). "In 2017, Animas Corporation, a subsidiary of Johnson & Johnson Diabetes Care Companies, declared the termination of its Animas Vibe and OneTouch Ping insulin pumps, signifying its departure from the insulin pump industry." (PMID 39065641, 2024). "Literature suggests that islet hormone secretion is regulated by glucose levels in the blood and decreased secretion during diabetes correlates with disrupted secretion of pancreatic hormones such as insulin, glucagon, and somatostatin." (PMID 38529398, 2024). "Treatment strategies for diabetes usually include regular blood sugar testing, insulin therapy, oral drugs, and lifestyle changes (diet, exercise, weight management)." (PMID 39224824, 2024). "The study included 522 patients with diabetes: 356 receiving insulin (group A), 70 receiving metformin (group B) and 96 healthy controls (group C)." (PMID 39495998, 2024). "This automated adjustment of insulin delivery can significantly improve glycemic control, thereby potentially improving the quality of life for individuals with diabetes." (PMID 39310514, 2024). "We use the streptozotocin-induced diabetes model with insulin supplementation, with 20-weeks diabetes." (PMID 38397785, 2024). "The DIATEC trial investigates the effects of an in-hospital diabetes team and operational insulin titration algorithms based on either continuous glucose monitoring (CGM) data or standard point-of-care (POC) glucose testing." (PMID 38711112, 2024). "Diabetes mellitus is a chronic condition characterized by elevated blood glucose levels resulting from insufficient insulin production or impaired insulin utilization in the body." (PMID 38726421, 2024). "Another interesting observation pertains to the age at which diabetes first manifests and its correlation with the utilization of insulin pumps." (PMID 39376804, 2024). "Diabetes mellitus (DM) is a persistent metabolic disorder associated with the hormone insulin." (PMID 38676028, 2024). "The selective up-regulation of the insulin mitogenic pathway as a result of hyperinsulinemia offers compelling evidence for the promotion of cancer growth in individuals with diabetes." (PMID 39692821, 2024). "The treatment of diabetes aims to control blood glucose levels, reduce insulin resistance, and enhance insulin production by the pancreas." (PMID 38726421, 2024). "Type 2 diabetes mellitus (T2DM) is a chronic metabolic disorder characterized by high blood sugar levels due to insufficient insulin production or insulin resistance." (PMID 39220736, 2024). "In advanced cirrhosis, exogenous insulin is frequently used to prevent hepatoxicity from other diabetes medications." (PMID 38254739, 2024).
diabetes (continued). "Over 90% of cases are type 2 diabetes mellitus (T2DM), whose development is primarily caused by a combination of a defective insulin secretion by pancreatic β-cells and the inability of insulin-sensitive tissues to respond to insulin." (PMID 39685901, 2024). "This complexity leads to variations in insulin resistance, production, and fat accumulation in ectopic places (liver, skeletal muscles, and pancreas), making tailored weight management for diabetes challenging." (PMID 38530928, 2024). "Diabetes mellitus (DM) occurs in patients with increased cellular resistance to insulin and/or decreased production and secretion of insulin by the pancreas." (PMID 39834923, 2024). "Some reports have indicated that diosgenin enhances the uptake of glucose in the cells, improves insulin signaling, and ameliorates diabetes effects." (PMID 38371502, 2024). "Insulin administration attenuates the neurochemical changes induced by STZ‐treated diabetes, as indicated by increased serotonin levels." (PMID 38639646, 2024). "At the end of the study, it was found that serum insulin levels, as well as brain and hippocampus Aβ-42 protein and tau protein levels, were significantly higher in the diabetes group compared to the control group." (PMID 38922352, 2024). "Eligible participants included adults with type 1 diabetes, type 2 diabetes on insulin, or diabetes of either type with A1c > 9%." (PMID 38980465, 2024). "This is thought to be due to decreased levels of serum sex hormone-binding globulin (SHBG) and increased levels of insulin in umbilical cord blood in pregnant women with diabetes, which interfere with testicular descent." (PMID 39439600, 2024). "The mean diabetes duration was 15.32 years (median: 15, SD:9.72), and the percentage of insulin users was 67.85%." (PMID 38656030, 2024). "More than half of patients diagnosed with pancreatic cancer eventually develop diabetes due to the destruction of insulin-producing cells." (PMID 38611003, 2024). "Linagliptin is commonly used in the treatment of type 2 diabetes mellitus, a condition characterized by elevated blood sugar levels due to the body’s impaired production or utilization of insulin." (PMID 38473837, 2024). "Diabetes is a complex, progressive, and chronic disease resulting from impaired secretion or sensitivity to insulin." (PMID 39064870, 2024). "To gain insights into the functional implications of these DEPS, we conducted pathway analysis using KEGG database, focusing on cancer-related pathways, insulin pathways, and type 2 diabetes mellitus pathways." (PMID 38272982, 2024). "Patients diagnosed with diabetes mellitus are frequently prescribed oral glucose-lowering drugs (OGLDs) and/or insulin and/or other injectable agents." (PMID 39020348, 2024). "T2DM represents the predominant form, encompassing 90% of all cases of diabetes mellitus (DM) and it results from inefficient utilization use of insulin." (PMID 38903536, 2024). "In rarer other forms of MODY patients have a “hyperinsulinemic” response to glucose, which is seen in most patients with insulin-independent forms of diabetes early in the natural history of the disease." (PMID 39902162, 2024). "The patient had a history of obesity (body mass index (BMI): 34), arterial hypertension, and type 1 diabetes mellitus treated with insulin (glargine-lispro)." (PMID 39156365, 2024). "Diabetes has emerged as one of the most serious threats to human health, and numerous insulin delivery systems have been developed to treat diabetes in recent decades." (PMID 38247784, 2024). "Treatment for resistance to insulin in diabetes type 2 mellitus using a plant-derived, natural, biocompatible insulin sensitizer that works with a nanodelivery technology." (PMID 39065620, 2024).